CDKN2A (cyclin dependent kinase inhibitor 2A)
Diseases named in the same sentence as CDKN2A in open-access papers (continued):
Sharing a sentence is not in itself a finding about the gene and the disease.
pancreatic cancer (continued). "In contrast, aberrant hypermethylation has been detected in tumor suppressor genes including PTEN, CDKN2A, and RASSF1A in pancreatic cancers." (PMID 26230721, 2015). "CpG island methylator phenotype (CIMP)-high status [three/four or more methylated promoters among CACNA1G, CDKN2A, IGF2, and RUNX3] was observed in 12% (34/283) of the pancreatic cancer cases." (PMID 25797243, 2015). "Several theoretically “actionable” aberrations exist in pancreatic cancer including, but not limited to, KRAS, CDKN2A, ARID1A, BRCA, PALB2, PIK3CA, BRAF and so forth." (PMID 25714017, 2015). "The P16INK4A/CDKN2A gene, located on the short arm of chromosome 9 (9p), is one of the most frequently inactivated tumor suppressor genes in pancreatic cancer." (PMID 24084722, 2013). "Deletion of CDKN2A/MTAP, one of the most prevalent oncogenic events across all malignancies, occurs frequently in many human tumors, including 53% of glioblastomas and 26% of pancreatic cancers." (PMID 39309689, 2024). "Contrary to prior beliefs, the study found that CDKN2B, rather than CDKN2A, plays a crucial role in inducing pancreatic cancer." (PMID 38666907, 2024). "Current CAPS and NCCN recommendations support pancreatic cancer screening for individuals with CDKN2A PVs, regardless of their family history." (PMID 35372037, 2022). "In another study of 727 patients with a family history of PDAC, including patients that did not meet the criteria for classification as familial pancreatic cancer, 6 (46.2%) of 13 CDKN2A VUSs identified were functionally deleterious in our assay." (PMID 35001868, 2022).
pancreatic cancer (continued). "CDKN2B (encoding p15INK4b) acts as a tumor suppressor by promoting cell cycle arrest and senescence in the absence of CDKN2A, especially in pancreatic cancer." (PMID 33660437, 2021). "They found that CDKN2A carriers worried more about developing pancreatic cancer than non-carriers at predisclosure, immediately post disclosure, and also 6 months later." (PMID 34748551, 2021). "Another disadvantage of the cfDNA panel used in this study was that it did not contain CDKN2A, a common mutant gene in pancreatic cancer." (PMID 32614932, 2020). "However, the importance of the major downstream target of CDKN2A deletion, PRMT5, in pancreatic cancer has seldom been discussed." (PMID 30922330, 2019). "Thus, the overall impact of a positive genetic testing for CDKN2A/CDK4 in the early detection and improved outcome of internal cancers and, in particular, of pancreatic cancer remains undetermined." (PMID 29774366, 2018). "Rarely, our institutions may test for CDKN2A or BAP1 as a single test, particularly if other cancers, such as pancreatic cancer or astrocytoma in the family, strongly suggest CDKN2A is the offending gene." (PMID 28283772, 2017). "LSM3 and TBX3 may also participate in cell cycle control; upregulation of LSM3 promotes proliferation of pancreatic cancer cells, and TBX3 may interact with the cell cycle protein CDKN2A." (PMID 17054779, 2006). "The surrogate role of CDKN2A is not clear, and the reported rate of MTAP loss in our cohort was low; the detection method for MTAP loss has not yet validated by comparative genomic hybridization for pancreatic cancer in our NGS testing panel." (PMID 38310130, 2024).
breast carcinoma (372 papers, 1999 to 2025). "Some types of cancers, such as HNSCC, neural system tumors, gastro-intestinal cancer, breast cancer, and lung adenocarcinoma, are reported in association with CDKN2A mutations." (PMID 38540309, 2024). "As for female breast cancer, a recent meta-analysis carried out across three large whole-exome sequencing datasets pointed to an association between deleterious protein-truncating or missense variants in CDKN2A and breast cancer at exome-wide significance." (PMID 39021548, 2024). "Researchers have shown that aberrant expression of CDKN2A is linked to the onset of malignant tumors such lung cancer, breast cancer, bone tumors, and skin cancer when homozygous deletion of CDKN2A is present." (PMID 38206516, 2024). "For example, The CDKN2A gene was found to be a potential addition to the small list of other genes examined for associations with breast cancer histopathology and/or disease course." (PMID 38539064, 2024). "Associations between predicted deleterious rare missense or protein-truncating variants and breast cancer were additionally identified for CDKN2A at exome-wide significance." (PMID 37592023, 2023). "There have been some previous suggestions that deleterious germline CDKN2A is associated with breast cancer risk." (PMID 37592023, 2023). "During breast cancer, CDKN2A expression is reduced in 83% of cancer-associated fibroblasts as compared with their normal adjacent cancer-free counterpart tissues isolated from the same patients." (PMID 37681908, 2023). "It has been shown that mutations in both RB and CDKN2A leads to resistance of rapamycin-mediated cell death in breast cancer cells." (PMID 36499727, 2022). "Despite rare alterations of this gene in breast cancer (approximately 5.8%), CDKN2A deletions were reported to be associated with poor outcomes in luminal B ER + patients." (PMID 35562750, 2022). "Bioinformatics studies have found that CDKN2A is also associated with breast cancer, prostate cancer, and colorectal cancer." (PMID 35035831, 2022). "When analyzing breast cancer tumors, including IDCs and ILCs, we observed new mutations in CDKN2A, RB1, CCND2, and CCND3 in the brain metastases of four IDCs, but not in their primary tumor counterparts." (PMID 36507516, 2022). "In our current study, we comprehensively analyzed the expression profile and stage characteristics of these CRGs in breast cancer, finding that CDKN2A, PDHA1 and LIPT1 expression were associated with pathological stage of BC." (PMID 36518756, 2022). "While ERα is the primary oncogenic driver in ER+ breast cancer cancers, other genetic alterations such as cyclin D1 overexpression in 50% of breast cancers and CDKN2A loss, contribute to disease progression and therapeutic response." (PMID 33741974, 2021). "This kinase is encoded by the CDKN2A gene, and it has been shown to be increased in women with breast cancer exposed to chemotherapy." (PMID 32928147, 2020). "For example, PVs in ATM and BRCA1 were significantly associated with >twofold increased risk for colorectal cancer and PVs in RAD51D and CDKN2A were significantly associated with >twofold increased risk for breast cancer." (PMID 31406321, 2020). "The association of germline CDKN2A PVs with increased breast cancer risk is of particular importance because, to our knowledge, this has not been reported previously." (PMID 31406321, 2020). "TCGA analyses showed that MYC, PIK3CA, and CDKN2A/B are the most frequently amplified, mutated, and deleted genes, respectively, in breast cancer." (PMID 32498332, 2020).
breast carcinoma (continued). "Among them, CDKN2A showed a contribution to breast cancer risk that was comparable to that conferred by BRCA2, whereas RAD51C, RAD51D, BRIP1 were proven to be responsible for an increase in ovarian cancer risk." (PMID 31936873, 2020). "In contrast, mutations in the mismatch repair genes CHEK2 and CDKN2A collectively decreased from 4.89% to 2.52% in the context of personal history of breast cancer." (PMID 31497750, 2018). "Our results suggest that in breast cancer, the methylation status of CDKN2A exon 2 is weakly associated with the proliferative activity and the molecular subtype of the tumor." (PMID 28403857, 2017). "Kras mutations, Myc amplification and Cdkn2a/b deletions are somewhat over-represented when compared with their incidence in human breast cancer." (PMID 28430642, 2017). "Given the association of the CDKN2A rs11515 and the functions of proteins encoded at 9p21 in cancer, the current study investigated rs11515 genotypes in breast cancer." (PMID 26835415, 2015). "Beside rs2736098 in TERT, only the association of rs3731249 in CDKN2A was analyzed previously and significant correlation was identified for early-onset breast cancers." (PMID 24171766, 2013). "For the 12p11 (PTHLH), 5q11 (MAP3K1), and 9p21 (CDKN2A/B), we found uncorrelated SNPs that had stronger associations than the originally identified SNP in the breast cancer susceptibility region that should be replicated in the general population." (PMID 23544012, 2013). "There was also some marginal evidence that the minor allele of rs1011970 near CDKN2A/CDKN2B was associated with increased breast cancer risk (HR = 1.09, 95% CI: 1.00 to 1.18, P-trend = 0.048)." (PMID 22348646, 2012). "Loss of CDKN2A (encoding p16ink4a) expression, from methylation-induced CDKN2A promoter silencing, or mutations, is one alteration frequently observed in human breast cancers and cultured HMEC." (PMID 17233903, 2007). "Consistent with that research, the polymorphism correlation of the CDKN2A / B gene (rs10811661) was studied in 564 breast cancer sufferers and the outcomes confirmed that people with TT genotype have been extra susceptible to breast cancer." (PMID 37845622, 2023). "Furthermore, novel polymorphisms in human CDKN2A that were near the SNP in mouse Cdkn2a were shown to be associated with the risk of human breast cancers." (PMID 33804471, 2021). "Interestingly, one of the clear cell cases harbored a CDKN2A (P16INK4A) gene mutation; several studies have revealed mutations in this gene in a proportion of breast carcinomas [reviewed in10]." (PMID 32279409, 2020). "The observation that Suz12 deficiency in normal mammary cells leads to de-repression of cdkn2a, paralleling that seen with loss of Ezh2, would predict that loss of PRC2 function in breast cancer would result in decreased tumor proliferation via up-regulation of p16Ink4a and p14Arf expression." (PMID 30080881, 2018). "We checked whether the association between CDKN2A expression in metastatic lymph-nodes and the risk of brain metastases could also be found in primary breast cancers." (PMID 28445153, 2017). "Moreover, CDKN2A promoter methylation has been associated with a 6.58-fold increase of breast cancer risk and occurs frequently in mammary cells obtained from women with greater chances of developing breast cancer." (PMID 26318587, 2015). "In addition, a previous study showed that a germline mutation of CDKN2A increases the risk of breast cancer." (PMID 24982892, 2014). "Consistent with this hypothesis, a recent study demonstrated that telomere length shortening was significantly associated with hypermethylation of CDKN2A promoters in breast cancer." (PMID 23990928, 2013).
breast carcinoma (continued). "Recent genome-wide association studies of breast cancer have identified eight additional breast cancer susceptibility loci: rs1011970 (9p21, CDKN2A/B), rs10995190 (ZNF365), rs704010 (ZMIZ1), rs2380205 (10p15), rs614367 (11q13), rs1292011 (12q24), rs10771399 (12p11 near PTHLH) and rs865686 (9q31.2)." (PMID 22348646, 2012). "Interestingly, other studies have confirmed that CDKN2A methylation might be associated with metastasis in other cancer types, including gastric cancer, breast cancer and endometrial cancer." (PMID 39590385, 2024). "Among genetic factors that could account for a common heritability between nevus count and breast cancer, one potential candidate is CDKN2A, a tumor suppressor gene encoding cyclin-dependent kinase inhibitors known to be frequently mutated or suppressed in a number of cancers." (PMID 24915306, 2014). "For instance, preclinical evidence suggests that CDK4/6 inhibitors, already approved for use in breast cancer, exhibit antitumor effects on IDHm astrocytomas harboring a CDKN2A/B deletion." (PMID 40392514, 2025). "We developed a pyrosequencing assay to analyze CpGs in CDKN2A exon 2, which was previously found to be hypermethylated in breast cancer." (PMID 40649906, 2025). "Cross-correlation analysis of SSR1/RPL39L was found only in colon and lung cancers, and the cross-correlation of PPARGC1B/CDKN2A was found only in colon and breast cancers, R-values of breast, colon and lung data." (PMID 39940786, 2025). "CDKN2A induces cell cycle arrest in the G1 and G2 phases, thereby inhibiting cell proliferation and enhancing the sensitivity of breast cancer cells to chemotherapy." (PMID 39702350, 2024). "CDKN2A is recognized as a tumor suppressor in certain cancers, such as breast cancer, where it exerts its influence by regulating the cell cycle to inhibit excessive proliferation of cancer cells." (PMID 38888512, 2024). "Distribution of VUS in breast cancer predisposing genes were :APC:1(5.8%), ATM:2(11.7%), BRCA1:1(5.8%), BRCA2:5(29.4%), BRIP1:1(5.8%), CDKN2A:1(5.8%), CHEK2:2(11.7%), FANC1:1(5.8%), MET:1(5.8%), STK11:1(5.8%), NF2:1(5.8%)." (PMID 37277882, 2023). "Prognostic values of two cuproptosis-related genes in breast cancer, namely CDKN2A and SLC31A1, were then evaluated." (PMID 37884650, 2023). "Importance analysis identifies CDKN2A has a pivotal role in AI modeling, whose higher expression indicates worse prognosis in breast cancer." (PMID 37857018, 2023). "PDHB and CDKN2A expression were significantly higher in breast cancer tissues compared with control." (PMID 37353799, 2023). "High expression of CDKN2A and the accumulation of p16 was consistently observed in resistant breast cancer cell lines." (PMID 36765923, 2023). "In metastasis breast cancer cohort, we find CDKN2A also overexpressed in breast cancer tissues, especially in malignant subtypes (TNBC)." (PMID 37857018, 2023). "Here, we found that Doxo and Abe upregulated the expression of CDKN1A and CDKN2A, resulting in cellular senescence in breast cancer cells, which is consistent with previous reports." (PMID 37993606, 2023). "CDKN2A is correlated with many cancers such as bladder cancer, colorectal cancer, and breast cancer." (PMID 37711156, 2023). "In order to verify the regulation effects of CDKN2A/MAGEA4 in breast cancer progression, in vitro experiments are performed." (PMID 37857018, 2023). "Public data are collected from TCGA and GEO, local breast cancer cohort is collected to verify the expression level of CDKN2A." (PMID 37857018, 2023). "Matching with our results, promoter hypermethylation was reported to inactivate CDKN2A in sporadic parathyroid adenomas, breast cancer, periocular sebaceous carcinoma, and hepatocellular carcinoma." (PMID 37626750, 2023).